PIEZO1 (piezo type mechanosensitive ion channel component 1 (Er blood group))
Diseases named in the same sentence as PIEZO1 in open-access papers (continued):
Sharing a sentence is not in itself a finding about the gene and the disease.
lung carcinoma (17 papers, 2012 to 2026). "There are only three publications directly researching the association between Piezo1 channel and lung cancer cell migration." (PMID 41585435, 2026). "In agreement with this, depletion of Piezo1 in small lung cancer cell lines also caused decreased integrin activation." (PMID 33841141, 2021). "In contrast, the loss of PIEZO1 expression caused increased cell migration and metastasis in lung cancer cells." (PMID 29757938, 2018). "Notably, in lung cancer, PIEZO1 overexpression has been associated with improved overall survival, suggesting a divergent, potentially tumor-suppressive role in this context." (PMID 40724850, 2025). "In lung cancer, the function of PIEZO1 has been linked to disease development." (PMID 38494915, 2024). "A decrease in the expression of Piezo1 and a decrease in integrin-dependent migration have been observed in small cell lung cancer (SCLC), so it is believed that the loss of Piezo1 expression may be a cause of the increased invasion and metastasis of lung cancer cells." (PMID 36615408, 2022). "In summary, our study has revealed a negative regulatory role of the Piezo1 channel in mediating stiff matrix-induced lung cancer cell migration." (PMID 41585435, 2026). "This is the first study that reports a negative regulatory role of the Piezo1 channel in matrix stiffness regulation of lung cancer cell migration and the molecular mechanism involved." (PMID 41585435, 2026). "Different from what is observed in most solid tumors, the Piezo1 channel in lung cancer is down-regulated and negatively regulates cancer cell migration, but the underlying mechanism is still unclear." (PMID 41585435, 2026). "Herein, we investigated the role of Piezo1 channel in matrix stiffness regulation of lung cancer cell migration and the mechanisms in A549 cells growing on polyacrylamide (PA) hydrogels with different stiffness." (PMID 41585435, 2026). "Different from what has been observed in most solid tumors, the Piezo1 channel plays a negative regulatory role in lung cancer cell migration and lung cancer metastasis." (PMID 41585435, 2026). "Research indicates that Piezo1 expression is downregulated in non-small cell lung carcinoma cell lines, suggesting that Piezo1 acts as a tumor suppressor in lung cancer, inhibiting the migration and distant spread of lung cancer cells." (PMID 41017814, 2025). "On the other hand, studies in lung cancer have attributed high PIEZO1 levels to better patient outcomes." (PMID 38398074, 2024). "Piezo1 downregulation can accelerate cell migration in lung cancer by promoting ameboid-type migration." (PMID 34831037, 2021). "The promotion of migration by Piezo1 is not well understood in all settings, as in lung cancer where Piezo1 is often downregulated." (PMID 34831037, 2021). "Piezo1 has been observed to increase endothelial cell permeability in lung cancer through calpain activity by reducing tight junctions." (PMID 34831037, 2021). "To investigate the effects of matrix stiffness on lung cancer cell migration and the Piezo1 channel expression, we prepared PA gels with stiffness close to that of reported healthy (3 kPa, soft) or cancerous (10 and 20 kPa, stiff) lung tissues and cultured A549 or H460 cells on them." (PMID 41585435, 2026). "Clinical data from Public datasets and experimental data from limited researches suggest that the expression of Piezo1 channel is decreased in lung cancer and negatively correlated with lung cancer metastasis, but the underlying mechanism is unknown." (PMID 41585435, 2026). "Given the importance of ECM stiffness, interesting questions arise, namely, does the Piezo1 channel respond differently in lung cancer migration, does it still play an inhibitory regulatory role, and what molecular mechanism is responsible for such a unique role?" (PMID 41585435, 2026).
lung carcinoma (continued). "The findings described in this study provide a previously unrecognized mechanistic explanation and broaden our understanding of the molecular mechanism how the Piezo1 channel functions in lung cancer and provided opportunities for the development of new lung cancer treatment." (PMID 41585435, 2026). "In contrast, the Piezo1 expression was significantly down-regulated in lung cancer." (PMID 41585435, 2026). "The exception to the rule of Piezo1 supporting tumorigenesis is Piezo1’s role in lung cancer." (PMID 36837670, 2023). "Our immunohistochemistry results revealed that PIEZO1 was downregulated in lung cancer." (PMID 35747124, 2022). "It has been proved that Piezo1 was downregulated in small lung cancer cell lines, therefore Piezo1 might be a cancer suppressor which suggested to inhibit the cells migration and distant metastases in lung cancer in lung cancer." (PMID 35461277, 2022). "Therefore, it is interesting to examine whether the Piezo1 channel is engaged in regulating lung cancer cell migration through the Ca2+-dependent cofilin/actin polymerization/filopodia formation pathway." (PMID 41585435, 2026). "Collectively, our study has revealed that stiff matrix down-regulates the Piezo1 channel expression and thereby restrains the rise in the [Ca2+]i to facilitate cofilin phosphorylation and filopodia formation, leading to an increase in lung cancer cell migration." (PMID 41585435, 2026). "However, it remains unknown how the Piezo1 channel in lung cancer cells respond to substrate stiffness and related to stiff substrate-induced lung cancer cell migration." (PMID 41585435, 2026). "However, whether Piezo1 reduction in other cancers causes amoeboid migration remains unknown, and the paradoxical functions of Piezo1 in lung cancer and other cancers remain to be further investigated." (PMID 36230880, 2022). "PIEZO1 has been shown to influence the activation of the Wnt/β‐catenin pathway by regulating ROS levels in A549 cells, and EMT is known to play an important role in lung cancer progression." (PMID 38494915, 2024).
hepatocellular carcinoma (14 papers, 2022 to 2026). A malignant tumor that arises from hepatocytes. "In hepatocellular carcinoma, PIEZO1 levels were elevated in tumor samples and were associated with more advanced disease stages, consistent with our observations regarding tumor progression." (PMID 40724850, 2025). "Both bioinformatic analysis and in vivo experiments indicated that Piezo1 mediates matrix stiffness-induced angiogenesis in hepatocellular carcinoma (HCC)." (PMID 41437911, 2026). "Piezo1, a mechanosensitive Ca2+ channel, plays pivotal roles in liver diseases by regulating fibrosis, hepatocellular carcinoma, and iron metabolism." (PMID 41017814, 2025). "The regulatory functions of the Piezo1 ion channel in hepatic fibrosis, cirrhosis, and hepatocellular carcinoma have been previously discussed; however, emerging research suggests that Piezo1 also plays a critical role in other liver diseases." (PMID 41017814, 2025). "Overexpression and chemical activation in hepatoma cell lines of the R2456H and R2488Q PIEZO1 GoF mutants induced stronger Ca2+ influx than in cells expressing WT PIEZO1." (PMID 34779027, 2022). "This review aims to summarize Piezo1 expression and function; discuss its roles in fibrosis, hepatocellular carcinoma, iron metabolism disorders, and cholestasis; and distinguish established findings from hypotheses and highlight key gaps." (PMID 41017814, 2025). "Second, a previous study reported that Piezo1 activation inhibited Hippo pathway through regulating MAPK signaling pathway in hepatocellular carcinoma, so it is possible that other pathways may participate in Piezo1‐induced neuronal apoptosis." (PMID 39328029, 2024). "Piezo1 recruits Rab5c, a small GTPase, promoting hepatocellular carcinoma via TGF-β signaling." (PMID 37762011, 2023). "Hepatocellular carcinoma (HCC): In HCC, Piezo1 expression is markedly up-regulated and correlates positively with tumor aggressiveness and poor prognosis, suggesting that Piezo1 is a key driver of disease progression." (PMID 40821847, 2025). "In hepatocellular carcinoma (HCC), the Ca2+ reaction induced by Piezo1 activation can promote YAP phosphorylation, which is mediated by JNK and P38 cascade regulation." (PMID 38690080, 2024). "Piezo1 plays an increasingly physiological role in hepatocellular carcinoma (HCC)." (PMID 36615408, 2022). "Additionally, Piezo1 is necessary for MAPK and YAP activation and translocation in hepatocellular carcinoma through an independent Hippo signaling mechanism." (PMID 37762011, 2023). "Piezo1 significantly related to poor prognosis and promotes progression of hepatocellular carcinoma via activating TGF-β signaling, which suggesting that Piezo1 may serve as a novel prognostic predictor and the potential therapeutic target for HCC patients." (PMID 35461277, 2022). "However, whether and how the progression of hepatocellular carcinoma (HCC) regulated by Piezo1 remains elusive." (PMID 35461277, 2022).
pulmonary hypertension (14 papers, 2022 to 2025). Increased pressure within the pulmonary circulation due to lung or heart disorder. "We first discovered a substantial elevation in Piezo1 expression in old VSMCs, which was a pathological hallmark indicated in previous studies on vascular cells with pulmonary arterial hypertension and cardiomyopathy." (PMID 37941511, 2024). "Upregulation of the mechanosensitive channel Piezo1 may play a critical pathogenic role in the development of pulmonary vascular remodeling in pulmonary arterial hypertension and pulmonary hypertension." (PMID 38202621, 2023). "However, little is known about the fully pathogenic role of PIEZO1 in pulmonary arterial hypertension." (PMID 35883633, 2022). "In freshly isolated PAEC’s and PASMC’s from intrapulmonary artery rings in a rat model of chronic hypoxia-induced pulmonary hypertension, Yoda1, a Piezo1 agonist, was found to induce and activate the AKT-endothelial nitric oxide synthase (eNOS) pathway." (PMID 38033335, 2023). "Individuals with pathogenic variants in PIEZO1 have the risk of severe complications, including thromboembolic events and pulmonary hypertension after splenectomy, so it is not recommended for patients with PIEZO1 mutations." (PMID 40291177, 2025). "In conclusion, these studies further elucidate the role of Piezo1 in vascular remodeling in pulmonary arterial hypertension, which has the potential to be an effective intervention molecule and potential target of action in the treatment of pulmonary hypertension in the future." (PMID 36247424, 2022). "Recent works have shown that Piezo1 is upregulated in pulmonary arterial endothelial cells of patients with pulmonary arterial hypertension (PAH) and in pulmonary artery smooth muscle cells of mice and rats models with experimental chronic hypoxia-induced pulmonary hypertension (PH)." (PMID 35806388, 2022). "To test whether PIEZO1-mediated VEGFA production in neutrophils also plays a role in diseases characterized by disordered vascular homeostasis, we examine EC proliferation in WT and Piezo1-cKO mice exposed to LPS-induced acute lung injury or chronic hypoxia–induced pulmonary hypertension." (PMID 40454475, 2025). "We, therefore, suggest that Piezo1 is the initiating factor in the disturbance of Ca2+ homeostasis in PASMC in some types of PAH, for example, chronic thromboembolic pulmonary hypertension (CTEPH) and congenital heart disease-associated PAH." (PMID 36776977, 2023). "Piezo1 mediates arterial relaxation by promoting the production of NO in PAH and use of GsMTx-4-ameliorated experimental pulmonary hypertension in vivo." (PMID 35883633, 2022).
Obesity (13 papers, 2019 to 2025). Accumulation of substantial excess body fat. "SWELL1 and key markers of inflammation (NLRP3, NLRP6, IL1B, IL18 and IL8) were also upregulated in VAT in obesity and T2D being significantly associated (P < 0.01) with PIEZO1 levels." (PMID 39707172, 2024). "We found that the increased expression of PIEZO1 in VAT in obesity and obesity-associated T2D is primarily attributable to adipocytes and is closely associated with SWELL1 and inflammatory markers." (PMID 39707172, 2024). "Results showed increased (P < 0.05) transcript levels of PIEZO1 in patients with obesity and obesity-associated T2D in VAT." (PMID 39707172, 2024). "Obesity and obesity-associated T2D increased (P < 0.01) gene expression levels of PIEZO1 in VAT mainly due to adipocytes." (PMID 39707172, 2024). "Our data showed that gene expression levels of PIEZO1 were increased in VAT from patients with obesity and obesity-associated T2D, being adipocytes the main responsible source for PIEZO1 expression." (PMID 39707172, 2024). "We aimed to determine the impact of obesity and obesity-associated type 2 diabetes (T2D) as well as mechanical compression forces on the expression of PIEZO1 in visceral AT (VAT) and its relation with inflammation." (PMID 39707172, 2024). "In summary, our studies add Piezo1 to a growing list of ion channels that are implicated in regulating insulin sensitivity, glucose metabolism and energy expenditure in obesity." (PMID 31263454, 2019). "Understanding the role of Piezo1 in macrophages could provide insights into how mechanosensitive pathways contribute to obesity-associated inflammation and metabolic dysregulation." (PMID 39707172, 2024). "Further research in this area may uncover novel mechanisms underlying the involvement of PIEZO1 in obesity and its associated comorbidities." (PMID 39707172, 2024). "Since activated PIEZO1 exhibits varying effects depending on the types and conditions of mechanical stimulation and the environmental context, the study of PIEZO1 in different AT depots will help to understand its role in obesity and its associated comorbidities." (PMID 39707172, 2024). "An important scientific finding is that PIEZO1 plays a central regulatory role in insulin sensitivity, glucose metabolism and energy expenditure in obesity." (PMID 39519393, 2024). "The treatment of THP-1-derived macrophages with the secretome of adipocytes from patients with obesity upregulated (P < 0.001) PIEZO1 levels." (PMID 39707172, 2024). "The effect of bariatric surgery on the expression of Piezo1 was assessed in a rat model of diet-induced obesity." (PMID 39707172, 2024). "Emerging evidence suggests the important role of PIEZO1 as a mechanosensitive ion channel in AT biology, energy metabolism, and the development of obesity-related metabolic disorders by impacting on AT mechanotransduction and inflammation." (PMID 39707172, 2024). "The analysis of the methylation levels of CpG-cg05831083 and CpG-cg14926485 in both obese and normal groups will help us understand the role of epigenetic changes in TFAM and PIEZO1 in obesity." (PMID 38505098, 2024). "Conversely, PIEZO1 CpG-cg14926485 exhibits high sensitivity and low specificity, suggesting its accuracy in correctly identifying obesity." (PMID 38505098, 2024). "This hypermethylation possibly increases the PIEZO1 gene expression in childhood with obesity, contributing to its development." (PMID 38505098, 2024). "The expression of Piezo1 was significantly increased in the white adipose tissue of obese mice, the mechanism of Piezo1 in obesity and insulin resistance needs further study." (PMID 35154133, 2022). "The results suggest that Piezo1 is necessary for restraining pro-inflammatory response and lipolysis in obesity." (PMID 31263454, 2019). "The insulin resistance in the HFD-fed adipose-Piezo1−/− mice indicates that the upregulation of adipose Piezo1 in obesity is likely adaptive." (PMID 31263454, 2019).
Obesity (continued). "The specific CpG sites, CpG-cg05831083 within TFAM and CpG-cg14926485 within PIEZO1 may serve as the potential biomarkers for diagnosing, treating, and preventing childhood simple obesity." (PMID 38505098, 2024). "By regulating ghrelin production, PIEZO1 has been also indirectly involved in obesity development." (PMID 39707172, 2024). "In this regard, Piezo1 activation in macrophages can influence processes such as phagocytosis, cytokine release, and immune cell migration, all of which are relevant in the microenvironment of adipose tissue in obesity." (PMID 39707172, 2024). "We did not quantify Piezo1 expression or activation in the gut, but future studies may explore if the level of Piezo1 expression or activation may vary in different conditions or disease states, for example, in patients with obesity or binge-eating disorder." (PMID 39759870, 2024). "Patients with obesity exhibited a downregulation of PIEZO1 together with an upregulation of ghrelin in the X/A-like cells maybe contributing to overeating and obesity." (PMID 39707172, 2024). "In addition, the increased expression of PIEZO1 in VAT in obesity and obesity-associated T2D, primarily attributable to adipocytes, is closely associated with SWELL1 and inflammatory markers." (PMID 39707172, 2024). "Thus, VRAC and Piezo1 both appear to be part of a complex regulatory system by which mature adipocytes control WAT homeostasis during obesity." (PMID 32385276, 2020). "Therefore, Piezo1 plays a key role in regulating adipose plasticity and insulin resistance in obesity." (PMID 31263454, 2019). "We found that Piezo1 is highly expressed in adipocytes and the expression is regulated in obesity." (PMID 31263454, 2019). "This suggests that Piezo1 not only participates in basic intestinal physiological functions but may also play a regulatory role in the development of metabolic diseases, such as obesity and type 2 diabetes." (PMID 41195420, 2025). "Thus, we propose that regulation of Piezo1 function could be a promising therapeutic approach for preventing and combating obesity and related metabolic disorders." (PMID 35725398, 2022). "Thus, adipose Piezo1 may serve as an adaptive mechanism for adipocyte plasticity restraining pro-inflammatory response in obesity." (PMID 31263454, 2019). "We then investigated whether adipose Piezo1 would be regulated in obesity." (PMID 31263454, 2019). "In line with our findings, upregulated Piezo1 levels in adipocytes but not in the SVF of AT from mice with obesity has been described, strengthening the involvement of PIEZO1 in the regulation of biological functions of adipocytes." (PMID 39707172, 2024). "Piezo1 -/- mice showed defects in the differentiation of adipocyte precursors into mature adipocytes when fed a high-fat diet (HFD), increased number of hypertrophic adipocytes, increased white adipose tissue (WAT) inflammation, and obesity, and reduced insulin sensitivity." (PMID 35154133, 2022). "Additionally, due to a lack of redundant samples, direct links between methylation and gene expression for TFAM and PIEZO1 in obesity and normal groups could not be established." (PMID 38505098, 2024). "Although we detected an increase in the amount of total immunostaining of PIEZO1 in VAT biopsies obtained from patients with obesity and T2D compared to that of volunteers with NW and with obesity and NG, differences were not statistically significant." (PMID 39707172, 2024).